CTLA4 (cytotoxic T-lymphocyte associated protein 4)
Diseases named in the same sentence as CTLA4 in open-access papers (continued):
Sharing a sentence is not in itself a finding about the gene and the disease.
melanoma (continued). "Our preclinical study demonstrated that combined PD-1/CTLA-4 blockade fails to reduce intracranial melanoma growth when mice are bearing tumors only in the brain." (PMID 38567052, 2023). "In the first instance, germ-free and ABX-treated mice were shown to have no response to the ICI in Ret-melanoma tumour models compared to controls of specific-pathogen free mice in which progression was halted by a CTLA-4 inhibitor." (PMID 35876944, 2022). "When combined with anti-CTLA-4 immune checkpoint blockade, MIF inhibition could overcome resistance to melanoma immune checkpoint blockade therapy by increasing CD8+ TIL, which may release IFN γ to induce ferroptosis, thus promoting antitumor responses." (PMID 35309911, 2022). "Augmented antigenicity enhanced infiltration of T cells carrying corresponding TCRs, sensitizing treatment-resistant B16F10 cells to in vivo PD-1 and CTLA-4 checkpoint blockade (however, these effects have only been tested in GVAX melanoma cells expressing GM-CSF)." (PMID 36497341, 2022). "It has been reported that the anti-CTLA-4 monoclonal antibody is not effective in melanoma with high glycolytic flux." (PMID 36620597, 2022). "Moreover, we also explored the distribution of IEGPI score in CR/PR and PD/SD, and the results showed that the patients with CR/PR had a higher IEGPI score (P<0.05) in melanoma patients receiving the both PD1 and CTLA4 treatment." (PMID 36147906, 2022). "To test this notion, we determined if CHI3L1 inhibits co-stimulation and stimulates the CTLA-4 axis without melanoma metastasis." (PMID 36618349, 2022). "In addition to its combination with anti-CTLA-4, T-VEC combined with pembrolizumab increased IFN-γ and CD8+ T cells in patients with advanced melanoma." (PMID 35292881, 2022). "Analysis from “VanAllen 2015” and “Snyder 2014” cohorts showed that ACAP1 expression in the non-response group was lower than in the response group of melanoma patients receiving anti-CTLA-4 therapy." (PMID 36497434, 2022). "Following the introduction of CTLA4 and PD1 immune checkpoint inhibitors, the optimal sequence of targeted therapy and immunotherapy for the treatment of patients with BRAF-mut melanoma is under investigation in clinical trials (DREAMseq [NCT02224781] and SECOMBIT [NCT02631447])." (PMID 35440004, 2022). "Increasing trends of IFN-γ production by CD8+ and CD4+ TILs were noticed in scrambled control but not IFNγR1KO melanomas upon anti-CTLA-4." (PMID 36008408, 2022). "In patients with prostate cancer and melanoma, MDSCs have also been reported as negative predictors of response to treatment with the anti-CTLA-4 mAb ipilimumab." (PMID 35017553, 2022). "In the context of malignant melanoma, CD16+ non-classical monocytes were shown to be crucial for ICI therapy, since they mediated the killing of regulatory T cells via a CTLA-4 (cytotoxic T lymphocyte-associated antigen 4)-specific mAb." (PMID 35954354, 2022). "Indeed, in melanoma patients, the specific CTL-intrinsic gene signature induced by CDK4/6i correlates strongly with favorable responses to anti-PD-1/L1 and anti-CTLA-4 therapy." (PMID 35444175, 2022). "A higher level of CTLA4 was found in these melanoma patients responding to ipilimumab treatment than in non-responders." (PMID 36233273, 2022). "In a separate study, mice bearing melanoma or sarcoma tumors and treated with broad spectrum antibiotics for 2 weeks were shown to have significantly worse survival with PD-1 and CTLA-4 blockade than mice not given antibiotics." (PMID 35474500, 2022). "This is in line with the well-known immunogenic nature of melanoma and the recent literature pointing at MHC-I/II protein expression as a powerful prognostic marker to predict the effectiveness of anti-CTLA-4 and anti-PD-1 immunotherapy in metastatic melanoma and other cancer types." (PMID 35805902, 2022).
melanoma (continued). "The overall study population was composed of 41 patients (25 males, 66.8 ± 9.9 years) with different types of cancer (lung, breast, melanoma, mesothelioma and nasopharynx), the majority with lung cancer, who reported lung toxicity during treatment with PD-1, PDL-1 and CTLA-4 inhibitors." (PMID 36013328, 2022). "In recent decades, immune checkpoint inhibitors (ICIs) and anti-programmed cell death 1 (PD1) antibodies (Abs) have been recognized as anchor drugs for the treatment of advanced melanoma, with or without additional drugs such as anti-CTLA-4 Abs in combination." (PMID 36555362, 2022). "In melanoma studies, TIDE was found to be more accurate than other biomarkers, such as PD-L1 levels and mutant load, in the prognosis of first-line anti-PD1 or anti-CTLA4 antibody therapy." (PMID 35558081, 2022). "For example, miR-28 interacts with PD-1/PD-L1, BTLA, and Tim-3 in melanoma; miR-424 interacts with PD-1/PD-L1 and CD80/CTLA-4 in OC; miR-128 interacts with B7-H3 and Gal-3 in CRC; miR-138 interacts with PD-1 and CTLA-4 in glioma." (PMID 36012588, 2022). "Despite existing approved monoclonal antibodies targeting CTLA-4, PD-1 and PD-L1 for the treatment of lung cancer, RCC and melanoma, amongst many others, the percentage of patients responding remains modest, although for those responding it is of major importance." (PMID 35251003, 2022). "A separate retrospective study of 27 melanoma patients who received infliximab for the treatment of immune-related colitis (with PDl-1 and/or CTLA-4 inhibitors) showed that cancer outcomes were not affected." (PMID 36081549, 2022). "Importantly TRM express an array of immune checkpoints such as PD-1, CTLA-4 and LAG-3, which are all current targets of ICIs in melanoma." (PMID 36466880, 2022). "We also predicted the potential responders with the SubMap analysis of a melanoma cohort receiving anti-PD-1 and anti-CTLA4 therapies, demonstrating that patients in the HEXP group are more likely to be sensitive to both anti-CTLA4 and anti-PD-1/PD-L1 therapies." (PMID 36468024, 2022). "In addition, an in vivo study recently demonstrated improved survival (orthotopic melanoma tumors) and slower tumor growth with SuccFerr-loaded LNC (intraperitoneal injection) compared to anti-CTLA4 mAb." (PMID 35889527, 2022). "According to this study, CIAI could serve as a precise prediction model for ICI therapy strategy making, along with existing predictors such as PD-L1/PD-1 and CTLA-4 expression level, TMB and melanoma subtypes." (PMID 36034849, 2022). "Among the six collected datasets, we observed significantly higher TMB in responders of NSCLC and melanoma samples who received anti-CTLA4 blockade therapy but not in anti-PD1 treated melanoma samples." (PMID 36139377, 2022). "Lastly, our cohorts did not include patients on anti-PD-1 plus anti-CTLA-4 combination therapy which limits the generalizability of our model on such treatment which has been incorporated in advanced melanoma first-line treatment." (PMID 36428698, 2022). "Soluble CTLA‐4 is derived from an alternatively spliced isoform of full‐length CTLA‐4 and secreted by several cell types including regulatory T cells (Treg), monocytes, melanoma cell lines, and pituitary gland cells." (PMID 35435327, 2022). "In BRAFV600E inhibitors (BRAFi)-resistant melanomas, the addition of MDSC depletion/blockade (anti-Gr-1 + CCR2 antagonist) prevented outgrowth of BRAFi-resistant tumors, although combination checkpoint blockade (anti-CTLA-4 + anti-PD-1) was ineffective." (PMID 35003065, 2021). "Clinically, despite the lack of prospective data with a control arm, electroimmunotherapy (ECT plus either anti-CTLA-4 or anti-PD-1) has shown favorable efficacy without apparently increasing toxicities in several advanced melanoma cohorts." (PMID 33808884, 2021).
melanoma (continued). "In a combinatorial study, anti-PD-1 mAbs, used either as single-agent or in combination with anti-CTLA-4 mAbs have been tested on patients with melanoma and non-small cell lung cancer (NSCLC) and IL-8 levels were monitored." (PMID 35011682, 2021). "Compared to anti-PD-L1 monotherapy, the combination of anti-PD-L1 and anti-CTLA-4 antibodies did not alter tumor eradication in the mouse melanoma model, despite an increase in highly motile T cells in the peri-tumoral area." (PMID 34572844, 2021). "Another limitation of this study is that we did not analyze melanoma samples from patients who were treated with anti-CTLA-4 monotherapy and therefore cannot conclude to what extent PD-L1 expression plays a role in these patients." (PMID 34621681, 2021). "Current clinical ICI applications target CTLA-4, PD-1, or PD-L1 molecules, and the FDA has approved ICI therapies in multiple malignancies, including melanoma, Merkel cell, non-small cell lung, head and neck, gastroesophageal, renal, bladder, and hepatocellular cancers." (PMID 34512641, 2021). "One of the major breakthrough in the treatment of tumor patients during the last decade was the introduction of blocking antibodies against immune checkpoint (ICP) receptors, especially against CTLA-4 and PD1, leading to long-term tumor control in melanoma, NSCLC and renal cell carcinoma patients." (PMID 34054844, 2021). "Furthermore, ECT and CTLA-4 and PD1 inhibitors have been evaluated in a retrospective study of melanoma patients." (PMID 34358144, 2021). "Indeed, ipilimumab (Yervoy®), a CTLA-4 inhibitor, has shown efficiency in the reconstitution of the anti-tumor immune response and was given FDA approval in 2011 for the treatment of melanoma." (PMID 34572799, 2021). "In melanoma anti-PD-1 and anti-CTLA-4 based immunotherapies improve survival significantly in advanced cases while targeting CD38 in melanoma TME could provide synergistic effects." (PMID 33727923, 2021). "Additionally, concomitant CTLA-4 blockade and ICOS engagement by tumor cells that express ICOSL significantly improved rejection of established melanoma and prostate cancer in mice." (PMID 33777008, 2021). "Staging examinations revealed progressive melanoma brain metastases and despite 2 further cycles of combined anti-PD1 and anti-CTLA4 immunotherapy followed by 1.5 cycles of Fotemustine, the patient died 22 months after the development of the scleroderma-like skin changes." (PMID 33879687, 2021). "Furthermore, considering that current standard-of-care strategies in melanoma often include a combination of anti-PD1 and anti-CTLA4 therapy, we treated B16 tumor bearing mice with this double combination." (PMID 33520112, 2021). "In Allen's melanoma cohort under anti‐CTLA4 therapy, no significant higher CYT was detected in B44‐present group, high‐TMB group, and B44‐present and High‐TMB group." (PMID 33411982, 2021). "Other cancer/drug histology differences reflected expected patterns; for example, CD274 (PD-L1) was significant in melanoma anti-PD-1 cohorts, but not anti-CTLA-4." (PMID 33508232, 2021). "The group also identified elevated numbers of this same CD4+ T cell subset in melanoma patients responding to anti-CTLA-4 antibody treatment, compared with non-responders." (PMID 34141724, 2021). "A negative prognostic effect of PD-L1 expressing CD8+ T-cells in melanoma has been reported in the context of anti-CTLA-4 immunotherapy and also in early stage melanoma without systemic treatment." (PMID 34071888, 2021). "This was the case with the 5555 BrafV600E melanoma cell line or even the parental MCA-205 line not expressing OVA when its immunogenicity was boosted by treating with the immune checkpoint inhibitor anti-CTLA-4 together with the immune stimulator poly(I:C)." (PMID 34081922, 2021).
melanoma (continued). "CTLA-4 maintains peripheral tolerance by enhancing regulatory T cell (Treg) functions; thus, undirected control of the effector T cells and overexpression of CTLA-4 in tumor samples implicates poor prognosis in patients with melanoma." (PMID 34526987, 2021). "Taken together, these results suggested that MAP2K1/2 gene mutations are a predictor for a favourable clinical response to anti-CTLA-4 therapy in metastatic melanoma rather than a prognostic factor for melanoma." (PMID 35069558, 2021). "Ipilimumab, an anti-CTLA-4 monoclonal antibody, has been found to significantly improve overall survival (OS) and progression-free survival (PFS) and increase the long-term survival rate of patients with advanced melanoma." (PMID 35069558, 2021). "We further discovered that PDCD1, CTLA4, TIM-3, LAG3, and RTP4 were upregulated in melanomas." (PMID 34154655, 2021). "To date, differential DNA methylation patterns have been identified between melanoma patients that were treated with anti-CTLA4 and that had a clinical benefit compared to those with no clinical benefit." (PMID 34944799, 2021). "Molecular imagery allowing for the mapping of cell proliferation identified secondary lymphoid tissues as the main site of lymphocyte proliferation following anti-CTLA-4 treatment, with no signals of significant proliferation in melanoma lesions themselves." (PMID 33602280, 2021). "In this study, we also observed that melanoma patients with and without COL3A1 mutations exhibited a survival difference in the setting of anti-CTLA-4 therapy, but not in the anti-PD-1/PD-L1 therapy." (PMID 35087523, 2021). "Melanoma bulk-tumor transcriptomic and single-cell (sc)RNAseq data have identified other potential biomarkers of response and survival in patients treated with sequential ICB therapy (anti-CTLA-4 then anti-PD-1)." (PMID 35087529, 2021). "This discrepancy may be due to the different melanoma models that were used, differential effects of IFNGR1KO vs. IFNGR1KD in tumor cells, and/or different types of ICBs (anti-CTLA-4+anti-PD-L1 vs. anti-CTLA-4 alone), which warrants further investigations." (PMID 34830176, 2021). "Therefore, the combination of anti CTLA-4 with axitinib, an inhibitor of VEGFR1, 2 and 3 was tested in subcutaneous and intracranial mouse models of melanoma." (PMID 34680355, 2021). "Noteworthy, a recent study also revealed that recurrent melanoma after ACT treatment exhibited high expression of IFN-γ signaling (PD-1, PD-L1, CTLA-4, though the picture was heterogeneous), which provided tractable targets for salvage immunotherapy, and indeed allowed for effective ICB." (PMID 34620200, 2021). "PD-L1 levels were up to three times higher on PMN-MDSCs from melanoma patients that failed to respond to ipilimumab treatment targeting CTLA-4 than in patients that responded promptly." (PMID 34203451, 2021). "Ipilimumab, a human IgG1κ anti-CTLA4 monoclonal Antibody (mAb), which binds CTLA4 and blocks its interaction with ligand CD80/CD86, was the parent ICI approved in 2011 by the Food and Drug Administration (FDA) for first and second-line therapy of melanoma." (PMID 33925884, 2021). "In one study, individual CTLA-4 antibody therapy and CCH ablation decreased the rate of contralateral tumor growth, but there was an even more significant decrease with combined therapy in both melanoma and hepatocellular carcinoma." (PMID 34136405, 2021). "We further explored differences between melanoma responders and non-responders by investigating the extent of (co-) expression of 6 functional markers (CTLA-4, Ki67, IDO, PD-1, PD-L1 and HLA-DR) in the FlowSOM clusters." (PMID 34071888, 2021). "High levels of MDSCs in patients with nonresectable melanoma negatively correlate with the clinical response to ipilimumab (anti–CTLA-4) (33, –35), and predicts failure of second-line immunotherapy with anti–PD-1 (nivolumab)." (PMID 33649199, 2021).
melanoma (continued). "In two previous retrospective studies, researchers have found that the overall survival of melanoma patients with signs of the abscopal effect after radiotherapy combined with CTLA-4 inhibitors was significantly longer than for those without." (PMID 34211459, 2021). "Surprisingly, preclinical studies examining the efficacy of MAPK/ERK inhibition with CTLA-4 blockade in melanoma are lacking." (PMID 34025662, 2021). "Anti-CTLA-4 antibody (Ipilimumab/Tramelimumab), approved for clinical management of CM more than five years ago and followed closely by the approval of anti-PD1 (Nivolumab), is the main immune therapeutical player that changed the fate of melanoma patients." (PMID 34575678, 2021). "TRAE spectra differ between patients receiving immunology as monotherapy or combined with ipilimumab (anti–CTLA-4); however, the immune-related AEs were similar to those after anti–PD-1/PD-L1 with or without ipilimumab in patients with advanced melanoma." (PMID 34858178, 2021). "The combination of targeted therapy and immunotherapy in melanoma has progressed in recent decades, including BRAF inhibitors and BRAF/MEK combination therapy and CTLA-4 and PD-1 inhibitors, whose efficacy in advanced stages of melanoma has been demonstrated in randomized trials." (PMID 35186949, 2021). "The expression of HLA-I APM components in biopsies of melanoma responsive to anti-CTLA-4 therapy was higher and survival was longer than among nonresponders." (PMID 34827646, 2021). "Consistently, combination therapy of anti–CTLA-4 and anti–PDL-1 mAbs plus an anticancer vaccine resulted in a significant increase in IFN-γ production by both CD4+ and CD8+ cells, which correlated with higher rates of melanoma tumor rejection." (PMID 33777008, 2021). "A study utilizing mass cytometry profiling of peripheral blood mononuclear cell (PBMC) samples from melanoma patients suggested a difference in anti-PD-1-treated but not anti-CTLA-4-treated patients." (PMID 35087529, 2021). "Whereas all naïve controls (n=15) developed melanoma in the brain and died within 35 days after B78 engraftment, 11 of 12 mice previously rendered disease-free by ISV + α-CTLA-4 rejected intracranial B78 melanoma engraftment, resulting in prolonged survival (p<0.001)." (PMID 32690669, 2020). "In melanoma therapy, anti-PD1 and anti-CTLA-4 antibodies have been approved." (PMID 32793150, 2020). "This study provides the first evidence that melanoma SK1 behaves as an immune escape lipid kinase, leading to an increased expression of immunosuppressive factors in the TME and impairing the response to anti-CTLA-4 or anti-PD-1 treatment." (PMID 31974367, 2020). "We mined the anti-CTLA-4 immune response dataset consisting of pre-treated melanoma samples from responders and non-responders to Ipilimumab for gene signatures pertaining to objective tumor response." (PMID 31991588, 2020). "In the same work, MHC class II expression in >1% melanoma cells was shown to predict response to anti-PD-1, but not to anti-CTLA-4 therapy." (PMID 32235439, 2020). "Combining oncolytic virotherapy and CTLA4 blockade resulted in rejection of distant (non-virally injected) tumors in the poorly immunogenic B16 melanoma model, which was dependent on NK cells and type I IFN." (PMID 32133005, 2020). "Using the colorectal tumor model MC38 and melanoma B16.F10, we showed that Aire−/− mice treated with anti-PD1 or anti-CTLA4 controlled tumor growth significantly better than the wild-type mice and was accompanied by an increased infiltration of activated CD8+ T cells into the tumors." (PMID 32641748, 2020). "The analysis of 457 publicly available samples revealed no predictive value of TMB in renal cancer and very weak in melanoma and lung cancer treated with anti-CTLA-4 drugs." (PMID 32517213, 2020). "Melanomas have the highest TMB and are usually quite immunogenic, which could explain the efficacy of anti-CTLA-4 in this model." (PMID 32326073, 2020).